MYO5B (myosin VB)
Diseases named in the same sentence as MYO5B in open-access papers (continued):
Sharing a sentence is not in itself a finding about the gene and the disease.
Hypoglycemia (1 paper, 2015). A decreased concentration of glucose in the blood. "Consistent with the phenotype observed in Myo5b knockout animals, the incapacity of newborn mice to overcome the postnatal hypoglycemia has been shown to be fatal within 18 h22." (PMID 26201991, 2015).
Insulin resistance (1 paper, 2019). Increased resistance towards insulin, that is, diminished effectiveness of insulin in reducing blood glucose levels. "MYO5B, DLG2, RHOU, and SNCA are novel biomarkers for the development of insulin resistance." (PMID 30678306, 2019).
ischaemic stroke (1 paper, 2023). "Similarly, other annotated mRNAs identified in the current study have been previously associated with a range of indications including liver injury (RAVER2,) and intestinal disease (MYO5B,), but have not been directly associated with ischaemic stroke diagnosis." (PMID 38007520, 2023).
leiomyoma (1 paper, 2023). A well-circumscribed benign smooth muscle neoplasm characterized by the presence of spindle cells with cigar-shaped nuclei, interlacing fascicles, and a whorled pattern. "For comparison of differential expression of genes in leiomyomas, there was a significant race/ethnicity correlation in expression for TNFRSF19, IRS4, PLEKHG4B, PGR, KRT17, CCDC177, MYO5B, and ZNF703." (PMID 37686244, 2023).
malnutrition (1 paper, 2024). Inadequate nutrition resulting from poor diet, malabsorption, or abnormal nutrient distribution. "The mucosal morphological changes observed in MYO5B-deficient mice could be due to malnutrition after the loss of apical nutrient transporters." (PMID 39404772, 2024).
metastatic tumors (1 paper, 2020). "MYO5B mutations were preferentially found in patients with metastatic disease and SDH deficiency (germline SDHB-mutations)." (PMID 32511227, 2020). "Here, we show a significantly stronger expression of MYO5B protein in metastatic tumors and much elevated mRNA expression levels (10-fold) in a subset of metastatic PPGL tumors." (PMID 32511227, 2020). "In contrast, metastatic tumors displayed a significantly stronger expression; 3/9 cases with intermediate expression and 6/9 displaying strong MYO5B expression compared to non-metastatic tumors (p = 0.007 by Mann-Whitney, 2-sided)." (PMID 32511227, 2020).
mucormycosis (1 paper, 2024). "Myo5B and other members of the myosin V family could be used as potential targets for future therapies to effectively treat mucormycosis." (PMID 39073411, 2024).
multiple system atrophy (1 paper, 2020). Multiple system atrophy (MSA) is a neurodegenerative disorder characterized by autonomic failure (cardiovascular and/or urinary), parkinsonism, cerebellar impairment and corticospinal signs with a median survival of 6-9 years. "Additionally, SNPs in the common genes encoding EDN1 and MYO5B have been associated with multiple systems atrophy (which presents with parkinsonism) and loss of the sense of smell (an early non-motor PD-symptom), respectively." (PMID 32858884, 2020).
neural tumors (1 paper, 2021). "Furthermore, overexpression of MYO5B mutants, characteristic of neural tumors, accelerates cancer cell migration along with stimulation of cell proliferation." (PMID 33670106, 2021).
Polyhydramnios (1 paper, 2022). The presence of excess amniotic fluid in the uterus during pregnancy. "Patients with bi-allelic missense MYO5B mutations, for which the presence of fetal bowel abnormalities was reported, presented with isolated polyhydramnios." (PMID 35893420, 2022). "Together, the occurrence of polyhydramnios associated with MVID was not restricted to either the MYO5B, STX3, or STXBP2 variants." (PMID 35893420, 2022).
respiratory syncytial virus infection (1 paper, 2017). "The myosin Vb requirement for type I parainfluenza virus and respiratory syncytial virus infection prompted us to study whether myosin Vs were also playing a role in RV-B14 infection." (PMID 29215055, 2017).
Sleep apnea (1 paper, 2023). An intermittent cessation of airflow at the mouth and nose during sleep is known as sleep apnea. "The results showed that Lasso regression identified a total of seven genes as the characteristic genes of sleep apnea, which are: C12orf54, FOS, GPR1, OR9A4, MYO5B, RAB39B, KLHL4, as the core genes of follow-up research and construction of prediction models." (PMID 38077447, 2023).
sudden infant death syndrome (1 paper, 2025). Unexpected death in infancy which remains unexplained following autopsy, review of the medical history, and investigation of the death circumstances and death scene. "Heterozygous rare and likely pathogenic missense MYO5B gene variants (n = 6) were identified in three patients of a cohort of young patients (n = 95) who died of sudden cardiac death in the young/sudden infant death syndrome." (PMID 39969162, 2025). "Next-generation sequencing screened for MYO5B gene variants in a cohort of sudden cardiac death in the young/sudden infant death syndrome patients." (PMID 39969162, 2025).
vision disorder (1 paper, 2023). Any impairment to the vision. "Among the novel GWAS-identified associations with AL, our study revealed potential candidate genes, including SLC25A12, BMP3, RGR, RBFOX1, and MYO5B, which have all been linked to visual function or eye development and have been implicated in vision disorders." (PMID 37351342, 2023).
tumor (13 papers, 2011 to 2026). "MYO5B, a member of the myosin family, facilitates cytoskeletal remodeling and intracellular trafficking, and its dysregulation has been linked to enhanced tumor cell migration and invasion." (PMID 41596426, 2026). "Loss of MYO5B, encoding the recycling endosome–associated myosin Vb, is associated with tumor development and tissue architecture defects in the gastrointestinal tract." (PMID 31682603, 2019). "Moreover, an altered subcellular localization of the MYO5B protein to the membrane was observed in three metastatic cases, and the most prominent abnormal pattern was observed in the tumor case harboring the p.G1611S mutation." (PMID 32511227, 2020). "This suggests that LIMA1 can enter tumor cells through a specific mechanism, where it binds to MYO5B and co-localizes with it." (PMID 41596426, 2026). "By elucidating the LIMA1/MYO5B signaling axis, we provide a conceptual framework for osteocyte-based therapy and identify potential molecular targets for restoring bone–tumor homeostasis." (PMID 41596426, 2026). "Through these combined actions, LRP5-activated osteocytes, via LIMA1 and MYO5B, simultaneously suppress tumor growth, limit osteolysis, and alleviate the immunosuppressive milieu within the bone metastatic niche." (PMID 41596426, 2026). "Collectively, these findings demonstrate that LRP5-overexpressing osteocyte-derived CM exerts its anti-tumor effects on EO771 cells primarily through the LIMA1–MYO5B signaling axis, with LIMA1 acting functionally via MYO5B." (PMID 41596426, 2026). "Collectively, our findings define the LRP5/LIMA1/MYO5B axis as a novel signaling pathway that repurposes a canonical Wnt signaling component for tumor suppression." (PMID 41596426, 2026). "Together, these findings indicate that LIMA1 exerts its anti-tumor effects, at least in part, through interaction with MYO5B in EO771 cells." (PMID 41596426, 2026). "Of these, changes in MYO5B were of particular interest, as previous studies have demonstrated that its inactivation promotes tumor cell invasion and motility 35,36." (PMID 40083939, 2025). "Consistently, we also found that MSCMel up-regulated MYO5B, an actin-based molecular motor whose inactivation promotes tumor cell invasion and motility 35,36, supporting a possible link to tumor growth inhibition." (PMID 40083939, 2025). "This study observed a gradual reduction in MYO5B protein expression depending on the tumor grade, thus being higher in well-differentiated and lower in poorly differentiated tumors (histologic grades I and III, respectively)." (PMID 33670106, 2021). "For patient P31, two low frequent variants were found exclusively in the tumour biopsy (CEBPA: p.188_189del, VAF 10.3%; MYO5B: p.V1703A, VAF 10.1%)." (PMID 31767937, 2019). "The anti-tumor effect of LRP5-overexpressing osteocyte-derived CM was attenuated upon MYO5B knockdown, and functional rescue experiments further confirmed that the integrity of the LIMA1-MYO5B axis is essential for the anti-tumor activity of LRP5-overexpressing osteocyte-derived CM." (PMID 41596426, 2026). "We hypothesize that LIMA1 secreted by osteocytes may exert its effects by binding to MYO5B in tumor cells through mechanisms such as membrane fusion or endocytosis." (PMID 41596426, 2026). "Further screening of two public PPGL data sets revealed three additional MYO5B mutations; one germline mutation in a metastatic PCC (p.R1641C), and two mutations in PCC tumor cases with metastatic potential (PASS score = 10) or metastasized disease (p.V1261G and p.D530E respectively)." (PMID 32511227, 2020). "When myosin Vb is down-regulated; the inactivation of myosin Va may inhibit proliferation, invasion, and motility of tumor cells, whereas myosin Vb could promote these activities." (PMID 28903372, 2017).
tumor (continued). "Several of the upregulated genes encoded adhesion receptors, secreted proteins and cytoskeletal components, including CDH11, POSTN and MYO5B, along with RUNX1, a master regulator of differentiation processes in different tissues implicated in cell transformation and tumor progression." (PMID 21611158, 2011). "In contrast, our study uniquely targets tumor cells indirectly by modulating osteocytic LIMA1 secretion and its downstream interaction with MYO5B in cancer cells." (PMID 41596426, 2026). "Accordingly, some genes (like HMGA2, MYO5B, and PAK6) had the opposite roles of AS events from the same parental gene in tumor and healthy tissues." (PMID 34628367, 2021). "Interestingly, both MYO5A and MYO5B were found to interact with a key tumor suppressor, phosphatase and tensin homolog (PTEN), in neural cells; however, whether PTEN trafficking underlies functions of either MYO5A or MYO5B motors in cancer cells remains unknown." (PMID 33670106, 2021). "In summary, our data demonstrate that LRP5-overexpressing osteocyte-derived CM exerts anti-tumor and bone-protective effects in vivo, and that LIMA1 and MYO5B may be relevant factors contributing to these actions within the bone microenvironment." (PMID 41596426, 2026). "Opposite to myosin Va, myosin Vb is another member of the class V of unconventional, dimeric nonfilamentous myosins, whose inactivation accelerates tumor cell migration and invasion." (PMID 28903372, 2017). "By positioning LRP5/LIMA1/MYO5B as a functional axis linking osteocytes to tumor cells, we provide a mechanistic framework in which osteocytes are not passive bystanders but active organizers of local anti-tumor responses in bone." (PMID 41596426, 2026). "Unlike MYO5A, its close homolog, MYO5B, appears to act as a tumor suppressor." (PMID 33670106, 2021). "Computational analysis of RNA-sequencing data from UCEC patients revealed that the molecular motor Myosin Vb (MYO5B) was elevated in the beginning stages of UCEC and occurred in all patients regardless of tumor stage, tumor type, age, menopause status or ethnicity." (PMID 36662766, 2023).
cancer (11 papers, 2017 to 2026). A tumor composed of atypical neoplastic, often pleomorphic cells that invade other tissues. "Another mutant, myo2(E1338R), which impairs vacuole transport, is analogous to myosin Vb(R1641C), a variant associated with cancer." (PMID 40196620, 2025). "Since the MYO5B mutations were found to drive progression through downstream up-regulation of glucose metabolism genes, e. g. glucagon, we hypothesize that these mutations may fuel the pseudohypoxic state by altering glucose uptake in cancer cells." (PMID 32511227, 2020). "We predicted that elevated MYO5B in UCEC would influence cancer metabolism reprogramming and result in a worse prognosis." (PMID 36662766, 2023). "The reportedly contrasting functional roles of MYO5A and MYO5B in cancer are puzzling, given the high sequence and structural similarity of these motors." (PMID 33670106, 2021). "The high expression and altered subcellular localization of MYO5B protein in a few malignant tumors speaks for an important role in progression of PPGL." (PMID 32511227, 2020). "Emerging evidence also suggest that MYO5B proteins have an important role through differential expression in multiple cancer types." (PMID 32511227, 2020). "In conclusion, our study adds deeper insight into the complex genotype-phenotype correlation in PPGLs and also augments the emerging evidence of MYO5B's involvement in cancer." (PMID 32511227, 2020). "Furthermore, MYO5B was signified as a prognostic marker for CRC with its lower expression being associated with poor overall and disease-free survival of cancer patients." (PMID 33670106, 2021). "Notably, although myosin Vb is a recycling endosome–associated protein and implicated in cell polarity, cancer, and tissue architecture defects, the role of myosin Vb in mitotic cell division has not been addressed." (PMID 31682603, 2019). "For non-cancer studies, the miDRB-targeted exosome biogenesis genes for ferroptosis-inhibiting miRNAs are retrieved as follows: miR-19a-3p (SDC1, VPS4B, and MYO5B), miR-424-5p (VPS4A and MYO5B), miR-4291 (ATP9A, SMPD3, TSG101, and MYO5B), miR-522-3p (PDCD6IP), and miR-670-3p (CD34 and RAB27A)." (PMID 38892270, 2024). "Although MYO5B has not previously been examined in UCEC, we speculated that its role in trafficking of nutrient transporters in the setting of normal homeostasis may be hijacked to promote cancer cells." (PMID 36662766, 2023).
intestinal disease (6 papers, 2018 to 2023). "How do different biallelic MYO5B genotypes cause isolated hepatic or intestinal disease, or concomitant hepatic and intestinal disease?" (PMID 33525641, 2021). "The current study successfully used CRISPR/Cas9 approaches and deletion of Exon 5 in the MYO5B gene to generate an inducible mouse model of MVID that recapitulates intestinal disease in human MVID." (PMID 35887942, 2022). "The final diagnosis of microvillus intestinal disease (MVID) was made on the third month after extensive investigations using electron microscopic examination of intestinal biopsy and genetic confirmation, finding a mutation at the homozygous status of MYO5B gene." (PMID 30364420, 2018).
infection (4 papers, 2017 to 2024). The state of being infected such as from the introduction of a foreign agent such as serum, vaccine, antigenic substance or organism. "Highlighted genes, which were MYO5B loss-increased and Compound-1-reversed, were implicated in cellular stress responses induced by inflammation or infection." (PMID 39404772, 2024). "For instance, EspF recruits clathrin, AP2, early (Rab5a and EEA1) and recycling (Rab4a, Rab11a, Rab11b, FIP2, Myo5b) endocytic proteins to sites of infection." (PMID 31947656, 2020). "In polarized cells, the process involves Myo5b-dependent shuttling of basolaterally internalized cargoes to apical infection sites." (PMID 31242273, 2019). "We therefore investigated the T3SS dependence of the distribution of clathrin endocytic (CHC, AP2-α, Rab5a and EEA1) and recycling [Rab11a, Rab11b, Rab25, Myosin 5b (Myo5b)] components upon EPEC infection of polarized MDCK cells." (PMID 31242273, 2019). "From the ‘host cell perspective’, Myo5b motors are required to mobilize Rab11-positive recycling endosomes and their cargoes to host infection sites." (PMID 31242273, 2019). "Basolateral recycling plasma membrane cargoes, e.g. TfnR and AQP3, are sorted, likely by EspF and yet unidentified other effector proteins, to Rab11/Myo5b-positive apical recycling endosomes hijacked to the apical infection sites." (PMID 31242273, 2019). "Infection with these strains also prompted the recruitment of Rab11a and Myo5b at infection sites, where EspF and Map staining partially overlapped with Rab11a and Myo5b, suggesting that the effector proteins reside in close proximity to the host proteins." (PMID 31242273, 2019). "Expression of Myo5b-tail inhibited the recruitment of Rab11a and Tfn to the infection sites (yellow arrows), suggesting that Myo5b is involved in the trafficking of basolaterally internalized TfnR to the apical recycling endosomes at the infection sites." (PMID 31242273, 2019). "We show that type-III secreted components prompt the recruitment of clathrin (clathrin and AP2), early (Rab5a and EEA1) and recycling (Rab4a, Rab11a, Rab11b, FIP2, Myo5b) endocytic machineries to peripheral plasma membrane infection sites." (PMID 31242273, 2019). "Using immunofluorescent localization and immunoprecipitation, we show that myosin Va co-localized with RV-B14 exclusively after viral entry (15 min post infection) and that myosin Vb was present in the clusters of newly synthesized RNA in infected cells." (PMID 29215055, 2017). "As the movement of TfnR-Rab11 positive recycling endosomes is controlled by Myo5b motors, we asked whether Myo5b is involved in their recruitment at infection sites." (PMID 31242273, 2019). "In non-polarized cells, this process involves Myo5b-dependent shuttling of Rab11 endosomes and their cargoes from perinuclear slow recycling endosomes to peripheral infection sites." (PMID 31242273, 2019). "Infection with EPEC-wt induced Tfn endocytosis in Myo5b-FL or Myo5b-tail-YEQR, but not in Myo5b-tail or Myo5b-tail-QLYC expressing cells." (PMID 31242273, 2019). "Infection of these cells with EPEC-wt resulted in significant Tfn and Rab11a recruitment in Myo5b-FL or Myo5b-tail-YEQR, but not in Myo5b-tail or Myo5b-tail-QLYC expressing cells." (PMID 31242273, 2019).
genetic disorders (3 papers, 2018 to 2023). "In the last 5 years, new genetic disorders, such as TJP2, FXR, and MYO5B defects, have been demonstrated to cause a similar PFIC phenotype." (PMID 30367658, 2018). "We therefore suggest that functional studies should be introduced to intronic spliceogenic variants if MYO5B-associated FIC is strongly suspected; it has been reported that many deep intronic variants can disrupt splicing and thus can become a cause of genetic disorders." (PMID 40225142, 2023). "MID is a rare genetic disorder caused by mutations in the Myosin VB (MYO5B) gene leading to a lack of myosin Vb." (PMID 34327104, 2021).
bacterial infection (1 paper, 2019). "Ectopically expressed Myo5b-FL co-clustered with Rab11a and basolaterally internalized Tfn at apical bacterial infection sites." (PMID 31242273, 2019).
MYO5B also shares sentences with these, for which no sentence is quoted: Alagille syndrome (3 papers); pheochromocytoma (3); colon adenocarcinoma (2); Dubin-Johnson syndrome (2); arrhythmogenic right ventricular cardiomyopathy (1); biliary atresia (1); bladder cancer (1); bowel dysfunction (1); cardiac diseases (1); cholangiocarcinoma (1); CNS tumors (1); congenital enteropathy (1); Crigler-Najjar syndrome (1); cytomegalovirus infection (1); deafness (1); dyslexia (1); Fanconi anemia (1); galactosemia (1); gastric tumor (1); Infertility (1); inflammatory bowel disease (1); Jaundice (1); Kabuki syndrome (1); leukoplakia (1); Mitchell-Riley syndrome (1); myocardial infarction (1); osteosarcoma (1); Parkinsonism (1); primary adrenal insufficiency (1); Respiratory tract infection (1).
A further 6 diseases each share a sentence with MYO5B in 1 paper.